RAMP3 (receptor activity modifying protein 3)
Diseases named in the same sentence as RAMP3 in open-access papers (continued):
Sharing a sentence is not in itself a finding about the gene and the disease.
tumor (23 papers, 2005 to 2025). "In clinical samples of renal cell carcinoma, RAMP3 has shown to be predominantly expressed in inflammatory cells associated with the tumor whereas RAMP2 was mainly localized in the malignant cells." (PMID 33489885, 2020). "In renal tumours, for instance, RAMP2 was expressed in the tumour cells themselves, while RAMP3 elevation was found in inflammatory cells associated with the tumour, highlighting the importance of the interaction of the tumour with the microenvironment." (PMID 25475159, 2014). "RAMP3 is one of three members of the RAMPs family, with RAMP3 deletion leading to inhibition of tumor proliferation and metastasis." (PMID 40740229, 2025). "AM, CLR, RAMP2, and RAMP3 have been reported in renal cancer, and a high level of CLR has been associated with a high tumor grade." (PMID 36980580, 2023). "RAMP3 deficiency cancer-associated fibroblasts inhibited cell proliferation/migration and metastasis, and the activation of RAMP2 in RAMP3−/− mice blocked tumor growth and metastasis." (PMID 36980580, 2023). "In fact, subcutaneous transplantation of RAMP3-/- CAFs mixed with Pan02 cells into mice inhibited tumor growth." (PMID 35625516, 2022). "In contrast, RAMP3 blockade in the context of a healthy AM/AM1 signaling is expected to considerably suppress tumor metastatic capacity." (PMID 33489885, 2020). "RAMP3 inhibition resulted in reduced tumour development in vivo, with a lower tumour microvessel density compared with controls." (PMID 28845385, 2017). "The loss of microvessels within αAMRs or AM22-52-treated tumors suggests that AM stimulation of CLR/RAMP2/RAMP3-expressing tumor vasculature acts as a survival mechanism for proliferating tumor endothelium." (PMID 28178651, 2017). "It is noteworthy to mention that, in some tumours, RAMP3 is expressed alongside RAMP2 while in others only RAMP2 is present." (PMID 25475159, 2014). "Tissue microarray analysis of human colorectal tumours revealed a clear increase of AM, CLR, RAMP2, and RAMP3 staining in lymph nodes and distant metastasis when compared with primary tumours." (PMID 25475159, 2014). "In this model, selective activation of RAMP2 and inhibition of RAMP3 could suppress tumor metastasis." (PMID 36980580, 2023). "Furthermore, the expression levels of tumor growth-promoting factors were decreased, while the expression levels of tumor growth inhibitory factors were increased, in RAMP3-/- CAFs." (PMID 35625516, 2022). "Microvessel loss in the tumors treated with αAMRs may indicate that stimulation of the CLR/RAMP2/RAMP3-expressing tumor vasculature by AM is a survival mechanism rooted in the proliferation of tumor endothelia." (PMID 36497391, 2022). "AM impacts angiogenesis and tumor growth and binds to calcitonin receptor-like receptor/receptor activity-modifying protein 2 or 3 (CLR/RAMP2; CLR/RAMP3)." (PMID 36497391, 2022). "Adrenomedullin (AM), a multifunctional peptide plays an important role in angiogenesis and tumor growth through its receptors calcitonin receptor-like receptor/receptor activity modifying protein-2 and -3 (CLR/RAMP2 and CLR/RAMP3)." (PMID 28178651, 2017). "Adrenomedullin, the ligand for the CRLR/RAMP3 receptor dimer, functions as a growth factor in several human tumour cell lines, in addition to promoting angiogenesis in vivo via CRLR/RAMP3 and CRLR/RAMP2 receptor dimers." (PMID 15642117, 2005). "The coordinated downregulation of KLF4, OLR1, CSF3, WIF1, RAMP3, and AGER, may impair tumor-suppressive mechanisms, thereby facilitating cancer progression, including enhanced tumor growth, migration, invasion, and metastasis." (PMID 40797277, 2025). "Moreover, the use of a polyclonal antibody designed to block all the receptor components of AM (RAMP2, RAMP3, and CLR) decreased both proliferation and invasion of prostate cancer cells, tumor weight, metastasis, and lymphatic vasculature." (PMID 36980580, 2023).
tumor (continued). "Furthermore, the levels of the AM receptors RAMP1, RAMP2, RAMP3, and CRLR were also elevated as compared to their adjacent non-tumor gastric tissues by 60%, 61%, 58%, and 62%, respectively." (PMID 29179449, 2017). "An evaluation of molecular signatures based on tumor expression of 20 metastasis-associated microRNAs, a comparison of microRNA expression between tumor and adjacent benign tissue, or the tumor expression of five genes (HN1, RAN, RAMP3, KRT19 and TAF9) can also predict prognosis." (PMID 28943622, 2015). "Its interaction with RAMP3 on EC5 may promote endothelial cell survival and angiogenesis.In the context of tumors, this interaction could contribute to the formation of new blood vessels, thereby providing the tumor with essential nutrients and oxygen." (PMID 41394809, 2025). "On the other hand, in Ramp3-/- mice, although tumor growth and angiogenesis were not affected (with respect to Ramp3+/+ animals), tumors presented a less aggressive phenotype as indicated by the marked reduction in liver metastases as well as the number of PDPN-positive CAFs." (PMID 33489885, 2020). "In contrast, but consistent with public databases, all primary tumours had detectable message for CALCRL and all RAMPs with one cell line losing detectable CALCRL expression along with 3 xenografts, one xenograft losing RAMP2 and 7 cell lines and 5 xenografts having no detectable RAMP3." (PMID 30777055, 2019).
cancer (10 papers, 2017 to 2025). A tumor composed of atypical neoplastic, often pleomorphic cells that invade other tissues. "The observation means that RAMP2 activation and RAMP3 inhibition can suppress metastasis, and that deficiency of the AM/RAMP3 system inhibited metastasis via the modification of cancer-associated fibroblasts." (PMID 36980580, 2023). "RAMP2 suppresses cancer metastasis by maintaining vascular homeostasis and inhibiting vascular inflammation and pre-metastatic niche formation, while RAMP3 promotes cancer metastasis via malignant transformation of cancer-associated fibroblasts." (PMID 35625516, 2022). "The regulatory role of RAMP3 is significantly different in different cancers." (PMID 35847972, 2022). "The regulatory effects of RAMP3 varied significantly in different cancers." (PMID 33990633, 2021). "This study shows that RAMP3 may be specifically involved in many processes key for cancer metastasis and LOXL2 stimulates these actions upstream." (PMID 28845385, 2017). "In contrast, in RAMP3-/- mice, PDPN-negative benign CAFs predominates, resulting in a decrease in cancer malignancy." (PMID 35625516, 2022). "Transplantation of cancer cells into drug-inducible vascular endothelial cell-specific RAMP2 knockout mice resulted in enhanced metastasis to distant organs, whereas metastasis was suppressed in RAMP3-/- mice." (PMID 35625516, 2022).
heart diseases (1 paper, 2022). "How RAMP2 and RAMP3 are related to the pathogenesis of these various heart diseases requires further investigation." (PMID 35625516, 2022).
infection (1 paper, 2025). The state of being infected such as from the introduction of a foreign agent such as serum, vaccine, antigenic substance or organism. "Furthermore, PG-1 significantly downregulated key immune-associated genes, Cxcl9, Cxcl11, Tnfrsf9, Vdr and Ramp3, which were among the top 10 significantly upregulated genes post PCN033 infection." (PMID 41295668, 2025).
inflammation (1 paper, 2017). Aberrant reaction of the microcirculation characterized by movement of fluid and leukocytes from the blood into extravascular tissues. "The present findings suggest that AM acts on synovial macrophages through RAMP3 during synovial inflammation." (PMID 28299347, 2017).
metabolic disorders (1 paper, 2022). "On the other hand, CLR/RAMP3 signaling participates in the regulation of postmenopausal obesity and metabolic disorders as well as cardiac lymphatic vessel development." (PMID 36452323, 2022).
RAMP3 also shares sentences with these, for which no sentence is quoted: adrenocortical carcinoma (1 paper); atherosclerosis (1); autoimmune uveitis (1); Hypertension (1); hypothyroidism (1); liver cirrhosis (1); lymph node metastasis (1); manic episodes (1); medullary thyroid carcinoma (1); metastatic tumor (1); migraine with aura (1); osteoarthritis (1); pancreatic adenocarcinoma (1); parathyroid adenomas (1); pilocytic astrocytoma (1); renal carcinoma (1); type-2 diabetes (1); viral infection (1).